TLR3 (toll like receptor 3)
Diseases named in the same sentence as TLR3 in open-access papers (continued):
Sharing a sentence is not in itself a finding about the gene and the disease.
cognitive decline (2 papers, 2023 to 2025). "Identifying the probable function and mechanism of TLR3 in the cognitive decline caused by chronic pain is therefore of great interest." (PMID 37544956, 2023). "To expand our investigation, we proceeded to explore the consequences of neuronal-specific knockdown of TLR3 on nociceptive hypersensitivity and cognitive decline in mice following CCI." (PMID 37544956, 2023). "We used dsRNA/TLR3 inhibitor to study the effects of blocking the dsRNA/TLR3 pathway on chronic pain-induced cognitive decline." (PMID 37544956, 2023). "Taken together, targeting the dsRNA/TLR3 pathway may have potential clinical application prospects for the treatment of chronic pain with cognitive decline." (PMID 37544956, 2023). "Nonetheless, the contribution of TLR3 to the pathogenesis of cognitive decline after chronic pain remains unclear." (PMID 37544956, 2023). "Of note, the artificial synthetic dsRNA, poly (I:C) could exacerbate the cognitive decline induced by CCI through activation of TLR3." (PMID 37544956, 2023). "Therefore, in our current study, we first investigated whether released dsRNAs could trigger the upregulation of TLR3 and contribute to the development of cognitive decline in a mouse model of CCI." (PMID 37544956, 2023). "Thus, the dsRNA/TLR3 inhibitor could improve cognitive decline after CCI." (PMID 37544956, 2023). "Importantly, dsRNA/TLR3 inhibitors could also reverse the cognitive decline after CCI by blocking the binding of dsRNAs and TLR3, suggesting that the binding of dsRNAs and TLR3 was crucial for the progression of cognitive disturbance after chronic neuropathic pain." (PMID 37544956, 2023).
colon adenocarcinoma (2 papers, 2022). "The somatic mutation of eight risk PRGs (CASP4, GPX4, GSDMC, TLR3, NLRP1, PLCG1, IL18, and IRF1) hardly occurred in PAAD samples but were commonly observed in colon adenocarcinoma (COAD) and stomach adenocarcinoma (STAD) ones." (PMID 35000541, 2022).
colorectal tumors (2 papers, 2022 to 2023). "Furthermore, PHF8 mRNA levels negatively correlated with IFNG, TLR3, IFIH1, STAT1 and OASL expression, suggesting that PHF8 restrains adaptive immune responses in human colorectal tumors." (PMID 37454216, 2023).
congenital Zika syndrome (2 papers, 2023 to 2025). "The results of the study demonstrated a link between the existence of the T mutant allele in the SNP rs3775291 in the TLR3 gene and the risk of congenital Zika syndrome (CZS) in pregnant women who contracted the virus during pregnancy." (PMID 37510216, 2023).
epidermodysplasia verruciformis (2 papers, 2019 to 2025). A rare inherited genodermatosis characterized by chronic infection with human papillomavirus (HPV) leading to polymorphous cutaneous lesions and high risk of developing non melanoma skin cancer. "Examples of such diseases are TLR3, TRIF, or UNC93B1 deficiencies which predispose to HSV-1 encephalitis and epidermodysplasia verruciformis or CXCR4 deficiencies which predispose to HPV." (PMID 31191561, 2019). "This study demonstrates significantly reduced TLR3 and TLR9 expression in both normal skin and flat warts of Epidermodysplasia Verruciformis (EV) patients compared to immunocompetent individuals (NEV)." (PMID 41211638, 2025).
geographic atrophy (2 papers, 2016 to 2021). "TLR3 rs3775291 was associated with both geographic atrophy (GA) and neovascular AMD (nAMD), with marginally significant pooled-P values." (PMID 26796995, 2016). "A protective effect of a specific polymorphism in TLR3 (L412F variant, rs3775291) has been shown in geographic atrophy, but not with early AMD or CNV, as shown in a study in Caucasian Americans from three different regions (Utah, Maryland, Oregon)." (PMID 34445096, 2021).
Granuloma (2 papers, 2022 to 2024). A compact, organized collection of mature mononuclear phagocytes, which may be but is not necessarily accompanied by accessory features such as necrosis. "Hepatic granulomatous inflammation was significantly reduced in TLR3 KO mice as measured by granuloma cross-sectional area." (PMID 38172683, 2024). "Moreover, when Mtb-infected mice were treated with poly-ICLC to stimulate type I IFN production at a high level via TLR3 activation, significant increases in lung bacterial loads together with necrotic granulomas were observed, but this phenomenon did not occur in mice lacking IFNAR-137." (PMID 35672321, 2022).
Hantavirus infection (2 papers, 2018 to 2020). "Taken together, our in vitro observations would fit with hantavirus infection strongly inducing PD-L1 and PD-L2 by triggering TLR-3, which transmits downstream signals through the TIR-domain-containing adapter-inducing IFN-β (TRIF) pathway." (PMID 30559738, 2018). "Ocular features are among the most common presentations of PUUV hantavirus infection, although this may be not related to the TLR3 p.L412F variation at all." (PMID 32936395, 2020).
helminth infection (2 papers, 2017 to 2024). "Many triggers, such as mechanical injury, ligands for Toll-like receptor 3 (TLR3), TLR2 and NOD2, helminth infection, pro-inflammatory cytokines, and proteases, such as trypsin and papain, can cause the formation of TSLP." (PMID 39057040, 2024). "In summary, we provide here the first investigation of gene networks associated with TLR3/TLR4 signaling/cascade within PBMC during F. hepatica infection, which provides useful information for further investigating the roles of TLR3/TLR4 in single cell types, during helminth infection." (PMID 28487699, 2017).
hemophagocytic lymphohistiocytosis (2 papers, 2015 to 2022). "Lyst has been shown to play an immunoregulatory role in the proinflammatory responses of toll-like receptors (TLRs), namely of TLR3 and TLR4, and has been associated with hemophagocytic lymphohistiocytosis following Epstein–Barr infection in a human patient." (PMID 36142395, 2022). "Previous reports indicated that EBER1 could cause an IFN-β inducible immune response through TLR3 signaling in infectious mononucleosis, chronic active EBV infection and EBV-associated hemophagocytic lymphohistiocytosis." (PMID 26172457, 2015).
Herpes simplex infection (2 papers, 2021 to 2022). "The KEGG pathway analysis highlighted that a large number of genes that were up-regulated after infection with V2 were the same as those upregulated in response to Herpes simplex infection (genes Myd88, Irf7, H2-Q7, Casp8, Tlr3, Daxx, C3, H2-Aa, Oas2, Oas3, H2-T22, H2-T23 and Cd74)." (PMID 35458422, 2022).
hippocampal atrophy (2 papers, 2021 to 2023). "However, cathepsin H deficiency decreases hypoxia-ischemia-induced hippocampal atrophy in neonatal mice through attenuation of TLR3/IFN-β signaling, suggesting that this pathway may be neuroprotective." (PMID 37124206, 2023).
Human papillomavirus infection (2 papers, 2021 to 2022). "Some proteins from Class 1, along with some proteins from Class 2, are also associated with the human papillomavirus infection pathway, especially TLR3 induced-signaling that yields the transcription and secretion of IFN-β for the host immune response." (PMID 35178414, 2022).
Huntington disease (2 papers, 2023 to 2024). Huntington disease (HD) is a rare neurodegenerative disorder of the central nervous system characterized by unwanted choreatic movements, behavioral and psychiatric disturbances and dementia. "Recent studies showed that mt-dsRNAs could activate innate immune sensors such as Toll-like receptor 3 (TLR3) in vulnerable neurons of Huntington’s disease (HD) mice and liver cells during alcoholic stress." (PMID 38338781, 2024).
injury (2 papers, 2016 to 2025). Damage inflicted on the body as the direct or indirect result of an external force, with or without disruption of structural continuity. "Here we show that the antimicrobial protein REG3A controls TLR3-mediated inflammation after skin injury." (PMID 27830702, 2016).
Listeria infection (2 papers, 2012 to 2019). "Thus, IFN-β induction in response to Listeria infection relies in part on TLR3 and does not require TLR4." (PMID 22432012, 2012).
meningitis (2 papers, 2018 to 2024). A disorder characterized by acute inflammation of the meninges of the brain and/or spinal cord. "Consistently, in our study, Tlr2/4–/– and Tlr2/3/4/7/9–/– mice displayed comparable phenotypes, while the phenotype of Tlr3/7/9–/– mice was largely indistinguishable from that of WT mice, arguing against a key role of TLR3, -7, and -9 in pneumococci sensing and thus meningitis pathology." (PMID 38358825, 2024).
metastatic cancer (2 papers, 2024 to 2025). A carcinoma which has spread from the original site of growth to another anatomic site. "Our results can support the idea that TLR3/4-primed-MSCs can lead to innate immune-mediated cell death and modify tumour cell biology in invasive and metastatic cancers." (PMID 38698968, 2024).
metastatic disease (2 papers, 2012 to 2015). "LRV present in this subgenus may contribute to the destructive inflammation of metastatic disease either by acting in concert with other intrinsic “metastatic factors” or by independently preying on host TLR3 hypersensitivity." (PMID 22919688, 2012).
migraine (2 papers, 2022 to 2025). "Therefore, considering the potential involvement of TLR3‐mediated sterile neurogenic inflammation in the pathogenesis of migraine, we aimed to investigate the effects of Poly‐IC on migraine‐associated inflammation and the underlying mechanisms." (PMID 40406905, 2025). "However, there seem to be opposing conclusions regarding the association between TLR3 and migraines." (PMID 35987639, 2022). "Since CSD is associated with several neurological disorders, the role of TLR3 and its signaling pathway in migraine still requires further clarification." (PMID 40406905, 2025). "Considering this observation, we established an episodic migraine model via single injection of nitroglycerin into rats and verified that TLR3 is involved in the pathological process of migraine attack." (PMID 40406905, 2025). "Next, we used Poly‐IC, a double‐stranded viral RNA mimic that can stimulate TLR3, together with a specific inhibitor to investigate its effect on migraine‐like hyperalgesia." (PMID 40406905, 2025). "In summary, Poly‐IC protects against neurogenic inflammation via TLR3/TRIF signaling pathway activation in a migraine model." (PMID 40406905, 2025). "A promising new drug target for the migraine treatment: Poly‐IC delivery can activate TLR3/TRIF signaling pathway and exert protective effects by blocking pro‐inflammatory responses in migraine." (PMID 40406905, 2025). "The present study provides experimental evidence that Poly‐IC protects against neuroinflammation via the TLR3/TRIF signaling pathway in migraine." (PMID 40406905, 2025). "Poly‐IC exerts therapeutic effects against neurogenic inflammation via the TLR3/TRIF signaling pathway in an episodic migraine model." (PMID 40406905, 2025). "To comprehensively understand the functional impact of the TLR3/TRIF signaling pathway on the inflammatory response in migraine, we knocked down TRIF in primary cultured neurons via shRNA." (PMID 40406905, 2025). "TRIF knockdown consistently markedly increased the number of CGRP‐positive neurons even under Poly‐IC‐treated conditions, which suggests that reduced TRIF expression weakened the neuroprotective effects of TLR3 activation in migraine." (PMID 40406905, 2025). "A thorough understanding of the mechanisms by which Poly‐IC‐induced TLR3 activation preserves homeostasis in migraine is still needed." (PMID 40406905, 2025). "Although little research has been conducted on the relationship between TLR3 and migraine, there is direct and indirect evidence to suggest that TLR3 is associated with migraine." (PMID 35987639, 2022). "Apparently, research on the relationship between TLR3 and migraine is insufficient, and more research is needed in the future." (PMID 35987639, 2022). "Generally, these results indicate that NTG stimulation may increase TLR3 production during migraine attacks, whereas Poly‐IC can relieve hyperalgesia by further activating TLR3 expression." (PMID 40406905, 2025). "To date, several studies have shown that TLR2, TLR3, and TLR4 are associated with migraine." (PMID 35987639, 2022). "Therefore, the activation of TLR3/TRIF by Poly‐IC is a promising therapeutic strategy that could be used to counteract migraine attacks." (PMID 40406905, 2025). "We performed double immunofluorescence staining to label the TLR3 protein and cell type‐specific markers in TNC and illustrated the pivotal role of neurons in the pathogenesis of migraine, which is in line with these previous findings." (PMID 40406905, 2025). "Poly‐IC treatment significantly upregulated TLR3/TRIF expression, reduced the production of CGRP, c‐fos, and inflammatory cytokines, and alleviated allodynia in an animal model of migraine." (PMID 40406905, 2025). "As shown, Poly‐IC treatment increased TLR3/TRIF expression, suppressed the production of CGRP, c‐fos, and proinflammatory cytokines, and alleviated migraine‐like hyperalgesia." (PMID 40406905, 2025).
migraine (continued). "In this study, we observed that the activation of the TLR3/TRIF pathway by Poly‐IC treatment can inhibit inflammatory responses and reduce neurogenic inflammation injury in migraine." (PMID 40406905, 2025). "TLR3 expression was upregulated after NTG stimulation, whereas Poly‐IC‐treated rats presented a more enhanced TLR3 expression with less migraine‐like hyperalgesia." (PMID 40406905, 2025). "Overall, activation of the TLR3/TRIF signaling pathway, according to our study, is a potential therapeutic strategy to ameliorate proinflammatory activity and disease severity in migraine." (PMID 40406905, 2025). "Although the relationship between TLR4 and migraine is more well-studied than that between TLR2 and TLR3, the related upstream and downstream mechanisms still require significant research." (PMID 35987639, 2022). "Interestingly, inflammatory stimulation increased TLR3/TRIF production during migraine attacks, whereas further activation of TLR3/TRIF signaling by Poly‐IC relieved hyperalgesia and limited inflammation by increasing TLR3 and TRIF expression." (PMID 40406905, 2025). "Notably, the current literature provides little evidence of the role of the TLR3‐mediated signaling pathway in migraine pathogenesis." (PMID 40406905, 2025). "Poly‐IC (with or without a TLR3 inhibitor) treatment was performed before migraine induction." (PMID 40406905, 2025). "However, direct evidence of the role of TLR3 in migraine is still lacking." (PMID 40406905, 2025).
myositis (2 papers, 2012 to 2013). "Overall, this study demonstrates for the first time that mechanical stretch could be beneficial by reducing expression of muscle autoantigens and of pro-inflammatory TLR3 and may provide new insight to understand how resistance training can reduce the symptoms associated with myositis." (PMID 24224022, 2013). "Interestingly, in biopsies obtained from patients suffering from myositis, the proteins corresponding to these autoantigens as well as the potentially proinflammatory TLR3 and TLR7 receptors were found to be up-regulated in regenerating myoblasts." (PMID 24224022, 2013). "Interestingly, immature muscle precursors in myositis biopsy tissues have been recently demonstrated as an important source of IFN-β, which was, however, mediated by TLR-3 activation." (PMID 22577940, 2012).
pancreatic ductal adenocarcinoma (2 papers, 2019 to 2025). An infiltrating adenocarcinoma that arises from the epithelial cells of the pancreas. "By using immunohistochemistry in pancreatic ductal adenocarcinoma (PDAC) and multiple other cancer samples, here we found that cancer cell TLR3, a well-known cytoplasmic dsRNA sensor, translocated to the nucleus especially upon chemotherapy stress." (PMID 40675966, 2025). "Cox regression survival analysis of patients with pancreatic ductal adenocarcinoma related to clinicopathological characteristics and TLR1, TLR3, TLR5, TLR7, and TLR9 immunoexpression." (PMID 31314777, 2019).
periodontitis (2 papers, 2019 to 2025). An acute or chronic inflammatory process that affects the tissues that surround and support the teeth. "TLR3 activation may also provide regenerative potential in periodontitis." (PMID 40136681, 2025). "Hence, activation of TLR‐3 can promote inflammatory reactions and thus may play an important role in periodontitis progression." (PMID 31049957, 2019).
pituitary adenomas (2 papers, 2018 to 2021). "HHV-6B was recently implicated in the progression of invasive pituitary adenomas (PAs) through the toll-like receptor 3 (TLR3) signaling pathway." (PMID 30542640, 2018). "In an in vitro study, activation of TLR3 in the rat pituitary adenoma GH3 cell line induced proliferation, invasion and secretion of inflammatory cytokines." (PMID 33986756, 2021). "In pituitary adenomas (PAs), TLR3 is expressed in every PA sample and correlated with the invasion and proliferation of PAs." (PMID 33986756, 2021). "Rat pituitary adenoma G3 cells challenged with polyinosinic:polycytidylic acid (Poly(I:C)), a TLR3 agonist serving as a viral mimic, increased TLR3 expression and cell proliferation through the TLR3 signaling pathway." (PMID 30542640, 2018). "Initial data pointed to possible HHV-6B-induced TLR3, Bcl-2, and NF-κB up-regulation as well as down-regulation of cleaved caspase 3 in rat pituitary adenoma cells." (PMID 30542640, 2018).
poliovirus infection (2 papers, 2013 to 2024). An disease or disorder caused by infection with Enterovirus C. "Recent research indicates that the antiviral response to poliovirus infection includes pathways mediated by MDA5, TLR3, and the TLR adaptor MyD88, with TLR3 being the most profoundly upregulated." (PMID 39335111, 2024).
primary biliary cirrhosis (2 papers, 2010 to 2020). "A strong positive correlation between the mRNA levels of TLR3 and type I IFN in the liver was found in the patients with primary biliary cirrhosis, suggesting TLR3 signaling is involved in the pathogenesis of primary biliary cirrhosis." (PMID 20936107, 2010). "Further studies are required to clarify the role of TLR3 in primary biliary cirrhosis." (PMID 20936107, 2010). "It is believed that poly I:C activation of TLR3 signaling in biliary epithelial cells as well as hepatocytes and immune cells in the liver results in production of type I IFN, which subsequently contributes to the pathogenesis of primary biliary cirrhosis." (PMID 20936107, 2010).
prostate tumor (2 papers, 2021 to 2025). "Vaccination of mice with a DNA vaccine encoding the ligand-binding domain of the androgen receptor, a prostate tumor associated antigen, and combined with TLR3 and TLR9 agonists, resulted in secretion of type 1 IFN from antigen-presenting cells and suppression of TRAMP-C1 prostate tumor growth." (PMID 41012179, 2025). "As a member of the Toll-like receptor (TLR) family, previous studies had reported that TLR3 was abnormally expressed in a variety of tumors, including breast, ovarian and prostate tumors." (PMID 34266404, 2021).
Pruritus (2 papers, 2019 to 2025). Pruritus is an itch or a sensation that makes a person want to scratch. "TLR3 also affects the central perception of pruritus as it increases the frequency of short-term excitations and affects long-term synaptic plasticity." (PMID 40007792, 2025). "The production of nerve growth factor (NGF) as a peripheral mediator of pruritus seen in wild-type mice following the induction of dry skin-resembling lesions is also absent in TLR3−/− mice." (PMID 40007792, 2025).